EGFR (epidermal growth factor receptor)
Diseases named in the same sentence as EGFR in open-access papers (continued):
Sharing a sentence is not in itself a finding about the gene and the disease.
glioblastoma (continued). "Radiation-induced glioblastomas had a lower rate of EGFR expression and incidence of p16 alterations than spontaneous glioblastomas in previous studies." (PMID 39586842, 2024). "High understanding of the downstream pathways of EGFR in glioblastoma is needed to configure ideal multi-drug therapies targeting them." (PMID 38396993, 2024). "Preclinical studies of EGFR inhibitors in glioblastoma models have shown promising effects in reducing cell proliferation, inducing apoptosis, and inhibiting invasion and angiogenesis." (PMID 38396993, 2024). "We sought to examine the effects of BAY2402234 on cell viability and metabolic responses in patient-derived glioblastoma cells that differ in their EGFR gene." (PMID 39195509, 2024). "In this study, we found four glioblastoma harboring EGFR exons 2-7 skipping, also known as EGFRvIII, which is constitutively auto phosphorylated and inefficiently down regulated." (PMID 39087020, 2024). "EGFRvIII is a truncated isoform of the epidermal growth factor receptor (EGFR), belonging to a subfamily of receptor tyrosine kinases (HER1–4) mainly expressed in glioblastomas, and has been found to be a key target for organ tumors." (PMID 38919533, 2024). "It has been shown that about 54% of glioblastoma patients express the EGFR WT protein, while 31% of patients express EGFRvIII." (PMID 39195509, 2024). "Examples of such paracrine interactions include glioblastoma, where cancer cells expressing mutant EGFR stimulate the growth of tumor cells with WT EGFR through cytokine secretion (IL‐6 and LIF)." (PMID 37418588, 2024). "In conclusion, the era of precision oncology holds promise for targeting EGFR in glioblastoma, contingent on tailored treatments, effective blood–brain barrier navigation, and the exploration of synergistic therapies." (PMID 38396993, 2024). "EGFR signaling can also suppress m6A levels in glioblastoma by inhibiting ALKBH5 nuclear export, thereby enhancing the function of the m6A eraser." (PMID 38398118, 2024). "EGFRvIII, genomic variant III of epidermal growth factor receptor (EGFR), was also identified as an effective diagnostic and prognostic biomarker for glioblastoma." (PMID 39001524, 2024). "The study was conducted in a group of patients with relapsed or refractory glioblastoma multiforme with amplification of the EGFR gene." (PMID 39531784, 2024). "On the same line, Cetuximab, an EGFR inhibitor, when conjugated with fluorescent dye (IRDye 800), was used to identify glioblastoma tissue, with an optimal signal to background ratio and adequate tumor visualization according to preliminary data." (PMID 39823065, 2024). "The predominant genetic alterations cited in glioblastomas are related to alternative splicing, rearrangements, and amplification of the EGFR gene." (PMID 38932383, 2024). "Preclinical and clinical studies have shown that there are limitations in EGFR inhibitor efficacy in glioblastoma treatments." (PMID 38396993, 2024). "In our study, patients with high-grade glioma had the following mutational frequencies according to the tumor variety: glioblastoma (GBwt-IDH), in which mutations in the TERT promoter (13/22 Patients), and EGFR promoter (5/22 Patients)." (PMID 39767683, 2024). "Targeting the downstream intracellular pathways of EGFR variants, in addition to the ECD, is important to suppress glioblastoma progression." (PMID 38396993, 2024). "In particular, we analyzed PKR production in infected and uninfected cells, as well as EGFR gene expression in primary glioblastoma cells and the role of the cathepsins in determining virus mediated cytotoxicity in studied cells." (PMID 39772250, 2024). "Herein, we assessed the expression levels of circZNF609, circNFIX, miR-145-5p, and EGFR using quantitative polymerase chain reaction in glioblastoma patients and normal brain samples." (PMID 38866807, 2024).
glioblastoma (continued). "For example, glioblastoma patients with both TERT promoter mutations and EGFR amplification or wild-type IDH often have a worse prognosis compared to those with tumors with only one of these alterations." (PMID 39767571, 2024). "One of the crucial steps in the pathogenesis of glioblastoma is the mutation of the EGFR receptor, which can occur concurrently with the formation of hybrid genes (e.g., EGFR/SEPT14 and EGFR/TACC) (OMIM 131550; OMIM 612140)." (PMID 39022728, 2024). "These tests analyze tumor DNA and RNA to identify key genetic alterations, such as mutations in the IDH1 and IDH2 genes, MGMT promoter methylation, and EGFR amplification, which are pivotal in glioblastoma classification and prognosis." (PMID 39338377, 2024). "On the other hand, TAMs can secrete EGF, which stimulates EGFR in glioblastoma cells, thereby reinforcing the oncogenic circuit." (PMID 38515213, 2024). "EGFR gene amplifications are present in more than half of glioblastoma, while EGFRvIII, a truncated receptor resulting from the deletion of exons 2 to 7, is the most common EGFR oncogenic mutation in glioblastoma." (PMID 38928445, 2024). "The overexpression of epidermal growth factor receptor (EGFR) in several cancer types, including glioblastoma and head and neck cancers, makes it an attractive target for therapeutic intervention." (PMID 39768156, 2024). "An unintended consequence of EGFRVIII-targeted CARs, however, is that it can lead to the proliferation of EGFRVIII-negative-EGFR-positive glioblastoma, an example of antigen escape in action." (PMID 39364321, 2024). "miR-7 is an intronic microRNA that has been shown to promote photoreceptor differentiation and inhibit EGFR and Aky pathway in glioblastoma." (PMID 38639785, 2024). "The recent WHO update reclassifies all IDH-WT gliomas into glioblastomas based on molecular markers (presence of TERT promoter mutation, EGFR amplification, or chromosome seven gain and ten loss aberrations)." (PMID 38672254, 2024). "EGFR gene amplification is the most frequent genetic alteration in glioblastoma, leading to an overexpression of EGFR that occurs in approximately a half of GBMs." (PMID 39273661, 2024). "Based on EGFR-driven glioblastomas’ dependence upon EGFR in vivo and in vitro, it would be assumed that TKIs should stop tumor growth." (PMID 38396993, 2024). "Studying clinical trials highlights EGFR’s importance as a biomarker for patients with glioblastoma." (PMID 38396993, 2024). "Glioblastoma cells harboring mutant EGFR on ecDNA reduce EGFR copy number in response to tyrosine kinase inhibitor administration, conferring drug resistance." (PMID 38286829, 2024). "EGFR’s most important ligands in glioblastoma include epidermal growth factor (EGF) and transforming growth factor-alpha (TGF-α)." (PMID 38928445, 2024). "EGFR, which is overexpressed in 50–60% of glioblastomas and is minimally expressed in normal brain tissue, is an attractive target for precise tumor visualization." (PMID 39766452, 2024). "More recently, the combination of nimotuzumab with melatonin, which is known to disrupt EGFR in its intracellular segment, demonstrated increased cytotoxicity and apoptosis of cancer cells in vitro and in xenograft mouse glioblastoma models." (PMID 39518074, 2024). "Previously, it was shown that PTEN alterations prevailed in primary glioblastoma, with EGFR amplification, by contrast, in recurrent tumors." (PMID 39684714, 2024). "Recognizing and identifying EGFR mutants in each patient is a vast improvement in the direction of overcoming glioblastoma heterogeneity and establishing targeted EGFR treatment." (PMID 38396993, 2024). "Targeting conformally-active EGFR on small extracellular vesicles using a novel Charge-gated Ion Exchange Membrane sensor allows sensitive and non-invasive detection of Glioblastoma in human subjects from untreated plasma." (PMID 38830977, 2024).
glioblastoma (continued). "Epidermal growth factor receptor is classically amplified in glioblastoma, and a variant, EGFR variant III, is expressed on glioblastoma, making it an exciting potential target for CAR T cell therapy." (PMID 39364321, 2024). "EGFR is classically amplified and plays a key role in the progression and development of solid tumors including glioblastoma, non-small cell lung cancer, and breast, gastroesophageal, and colorectal cancer." (PMID 39364321, 2024). "In glioblastoma, receptor tyrosine kinases such as EGFR and VEGFR activate the PI3K‐AKT signalling pathway via tyrosine residue autophosphorylation, playing a pivotal role in tumour proliferation and progression." (PMID 38687049, 2024). "Disease stabilization was seen in 3 patients (14.3%), 2 of whom had glioblastoma (1 EGFR amplification, 1 EGFR wild type) and 1 who had EGFR wild-type chordoma." (PMID 38680990, 2024). "SPRED3, is reported to have an influence on EGFR mutated NSCLC, glioblastoma, and cervical carcinoma." (PMID 38217548, 2024). "A younger age of onset, higher tumor mutation burden and expanded G1/EGFR-mutant and G3/NF1 glioblastoma subgroups characterized the glioblastomas from African American/Black relative to Caucasian/White patients." (PMID 38254850, 2024). "In one, a polymalic acid-based nanoconjugate was attached to drugs targeting protein kinase CK2, EGFRvIII, and wildtype EGFR and was tested in glioblastoma mouse models." (PMID 38396993, 2024). "Although EGFR inhibitors have demonstrated efficacy in other cancers, their application in glioblastoma is hindered by blood–brain barrier penetration and intrinsic resistance." (PMID 38396993, 2024). "Overall, the results of preclinical studies suggest EGFR to be a promising glioblastoma therapeutic target, when targeted specifically and with the correct combination of drugs." (PMID 38396993, 2024). "EGFRvIII, which is expressed in 25% of EGFR-expressing glioblastomas, or the E6 and E7 proteins of HPV, which are expressed in approximately 60% of oropharyngeal cancers and almost all cervical cancers, or MAGE are all targets for shared antigens." (PMID 38785789, 2024). "Rolling-translated circEGFR binds to and stabilizes EGFR and correlates with glioblastoma tumorigenesis and nimotuzumab drug sensitivity." (PMID 39519039, 2024). "Targeting EGFR in glioblastoma should be aimed at glioblastoma-specific mutants, and an effective treatment should also suppress amplified wildtype EGFR." (PMID 38396993, 2024). "Another Mafodotin-based ADC, Depatuxizumab mafodotin, targets EGFR in glioblastoma and EGFR-overexpressed tumors." (PMID 38892287, 2024). "The design of new, highly specific antibodies targeting EGFR in glioblastoma has also been addressed thoroughly." (PMID 39518074, 2024). "Targeted therapies against EGFR have showed efficacy in other cancers, but their use in glioblastoma has yielded varied results, with some of their limitations including difficult blood–brain barrier (BBB) penetration and intrinsic resistance." (PMID 39518074, 2024). "Despite lacking RAS mutations, the protein is significantly activated in glioblastoma due to Receptor Tyrosine Kinase (RTK) activation, such as EGFR." (PMID 37762559, 2023). "EGFR was highly expressed with ≥32 transcripts per million (TPM) in glioblastoma (GBM), low-grade glioma (LGG), kidney renal clear cell carcinoma (KIRC), esophageal carcinoma (ESCA) and head and neck squamous cell carcinoma (HNSC)." (PMID 37370859, 2023). "Evidence suggests that EGFR is overexpressed in most primary glioblastomas and some of the secondary glioblastomas and is characteristic of more aggressive glioblastoma phenotypes." (PMID 37509607, 2023). "The Epidermal Growth Factor Receptor gene (EGFR) is one of the most frequently altered genes in glioblastoma." (PMID 37803333, 2023).
glioblastoma (continued). "EGFRvIII is the most common EGFR large fragment deletion identified in many malignancies, including glioblastoma, non‐small cell lung carcinoma, breast cancer, and ovarian carcinoma." (PMID 36622089, 2023). "In contrast, ELOVL2 depletion altered the phospholipid composition of the cell membrane by controlling fatty acid elongation, disrupting the structural characteristics of the cell membrane, and reducing EGFR signaling in glioblastoma cells." (PMID 37483592, 2023). "EGFR amplification was detected in 7% of total tumors; glioblastoma presented an amplification frequency that was greater than 40%." (PMID 37298484, 2023). "EGFRvIII-positive brain tumors were all glioblastoma with wild-type IDH1/2 status, most with EGFR amplification and EGFR mutation." (PMID 38201434, 2023). "Having determined the impact of enhancer perturbation on EGFR expression, we then evaluated the proliferative and invasive capacities of the enhancer-perturbed glioblastoma lines." (PMID 37803333, 2023). "Tumor development and progression of IDH wild-type glioblastomas are highly dependent on the overexpression of RTKs involving major signaling pathways such as the EGFR/PI3K/AKT/PTEN pathway but also on the involvement of metabolic pathways." (PMID 37626776, 2023). "Immunostaining is accomplished with fluorescent antibodies against EV markers such as CD9, CD63, and CD81 or cancer markers, in this particular study from three glioblastoma cell lines overexpressing EGFRvIII, EGFR, or IDH1‐R132." (PMID 35898167, 2023). "We found that there are distinct, significantly differentially methylated regions in glioblastomas correlating with EGFR amplification status." (PMID 37444635, 2023). "EGFR is among the most frequently deranged genes in glioblastoma (GBM), making it an attractive therapeutic strategy." (PMID 37669963, 2023). "Liposomes for co-delivering doxorubicin and erlotinib, an EGFR inhibitor, were designed by Lakkadwala and Singh (2019) for glioblastoma multiforme regression." (PMID 37273792, 2023). "The EGFR and TTN mutations were the most frequent mutations in glioblastoma of ArMRS low-risk group." (PMID 37214463, 2023). "Overexpression of WTAP facilitates renal cell carcinoma by stabilizing CDK2 transcript, and WTAP promotes the invasiveness of glioblastoma through enhancing the activity of EGFR." (PMID 36855062, 2023). "The activation of the receptor tyrosine kinase EGFR in glioblastoma cells leads to increased PI3K-AKT signaling and subsequent mTORC1 activation." (PMID 37834408, 2023). "To test this, we investigated the expression of inhibitory and activating immune checkpoint molecules as well as EGFR as an oncogenic factor in five human glioblastoma cell lines at basal level and after treatment with fractionated RT and/or TMZ." (PMID 36480032, 2023). "Our EGFR enhancer-repressed glioblastoma cells also present a reduced response to chemo-attractive stimuli and express less EGFR than the parental unmodified cells." (PMID 37803333, 2023). "In cell lines derived from glioblastoma patients, a sequence duplication was observed between EGFR and LINC01446, generating a “neo‐TAD” between the two adjacent TADs." (PMID 37426677, 2023). "PFKP induced PD-L1 expression through EGFR activation and promoted immune evasion in human glioblastoma cells." (PMID 37622118, 2023). "Analyses of copy number variation (CNV) plots that were checked routinely during sample workup (e.g., 1p and 19q losses) found that a subfraction of glioblastomas showed EGFR amplification." (PMID 37444635, 2023). "Recently, WTAP was found to be overexpressed in glioblastoma; its ablation repressed the migration and invasion of the glioblastoma cells by regulating EGFR activity." (PMID 37854284, 2023). "A patient with glioblastoma (P24) was identified with EGFR KDD and EGFR amplification in tumor tissue." (PMID 36325957, 2023).
glioblastoma (continued). "In our study using multiplex NGS, we observed EGFR amplification in 44% of glioblastoma and EGFRvIII in 14% glioblastoma, similarly to previous studies." (PMID 38201434, 2023). "In this study, we present an analysis comparing the transcriptomes of primary and recurrent glioblastoma samples, stratified by EGFR amplification status." (PMID 36765632, 2023). "Both studies observed EGFR amplification in a proportion of endothelial-like cells and suggested that these cells were of glioblastoma origin." (PMID 36823554, 2023). "Further investigations are essential for exploring the hidden mechanisms related to manipulating the EGFR pathway, therapy resistance, and the induction of ferroptosis in glioblastoma." (PMID 37947601, 2023). "The epidermal growth factor receptor (EGFR) has been designated as a “signature molecule” for glioblastoma." (PMID 37762559, 2023). "Mutated EGFR type III (EGFRvIII) is frequently found in approximately 50% of glioblastoma tumors that exhibit EGFR amplification." (PMID 38264122, 2023). "Serving as an EGF-independent EGFR-activator, C-E-Cad blockade dramatically enhances therapeutic effect of anti-EGFR strategy, which alone is proven ineffective for glioblastoma treatment." (PMID 38933287, 2023). "Compared to IDH1-mutant tumours, glioblastomas showed significantly higher expression of EGFR, MEOX2, and CD34 and significantly lower positivity for SOX11." (PMID 37568909, 2023). "On the contrary, the mutation of PTEN, EGFR, TTN, NF1, SPTA1 and RB1, which occurred frequently in glioblastoma, were more frequently in PVT1 higher group." (PMID 37202742, 2023). "D2C7-(scdsFv)-PE38KDEL is a recombinant pseudomonas exotoxin-A conjugated to antibody targeting both the wildtype EGFR and mutant EGFRvIII, both of which are highly expressed in glioblastomas." (PMID 37568717, 2023). "For that purpose, we have used luciferase-expressing glioblastoma cell line (U251 Luc), naturally expressing both EGFR and GD2 on its surface, which was confirmed by staining with anti-GD2 and anti-EGFR mAbs." (PMID 37122703, 2023). "YTHDF2 has been shown to contribute to glioblastoma cell proliferation and tumorigenesis, and overexpression was mediated in glioblastoma via the EGFR/SRC/ERK pathway." (PMID 37444417, 2023). "A tumor‐expressed deletion mutant of the epidermal growth factor receptor (EGFRvIII) is a robust CAR T cell target in glioblastoma." (PMID 36890859, 2023). "In glioblastoma models, EGFR activation induced c-Src-mediated phosphorylation of CD47, which prevented its interaction with the E3 ubiquitin ligase, TRIM21, and protected CD47 from ubiquitin-associated degradation." (PMID 37958404, 2023). "Frequent and diagnostically relevant molecular alterations in IDH-wildtype glioblastomas include TERT promoter mutations, EGFR gene amplification, and copy number gain in chromosome 7 combined with copy number loss in chromosome 10 (+7/−10 genotype)." (PMID 38201434, 2023). "We aimed to evaluate the mutation profile, transcriptional variants, and prognostic impact of the epidermal growth factor receptor (EGFR) gene in isocitrate dehydrogenase (IDH)‐wildtype glioblastomas (GBMs)." (PMID 35695190, 2023). "In 2022, Kasenda and group, for the first time in a phase I trial, clinically assessed the capacity of EGFR-targeted immunoliposomes in delivering the cargo to brain tissue in patients with relapsed EGFR amplified glioblastomas." (PMID 37483515, 2023). "CDK2, which is often upregulated in GBMs compared to normal brain tissue, has been shown to be downstream EGFR target in glioblastoma cell lines." (PMID 37936247, 2023). "EGFR amplification is a particularly common feature of glioblastoma, a large proportion of CNS tumors, and we see this reflected in more extreme metric values for CNS tumors." (PMID 37385267, 2023).